TSSK6 (testis specific serine kinase 6)
Description:
Serine/threonine-protein kinase component of the sperm flagellar doublet microtubules. May act as a regulator of sperm motility by mediating phosphorylation of sperm doublet microtubule proteins (By similarity). Plays a role in DNA condensation during postmeiotic chromatin remodeling and histone-to-protamine transition during spermatogenesis (By similarity).
Synonyms: TSK-6; CT72; SSTK; FKSG82; FLJ24002
Tractability: Small molecule: a high-quality ligand is known; it belongs to a druggable protein family. PROTAC: UniProt records ubiquitination sites on it; a small molecule that binds it is known.
Target class: CAMK protein kinase TSSK family; CAMK protein kinase group; Protein Kinase; Enzyme; Kinase
Gene: Protein-coding gene on chromosome 19 (19,512,418 to 19,515,548, reverse strand). Ensembl gene ENSG00000178093.
Subcellular location: Cytoplasm, cytoskeleton, flagellum axoneme; Nucleus
Subcellular location (Human Protein Atlas): Nuclear bodies
Gene Ontology:
Molecular function: ATP binding; magnesium ion binding; protein binding; protein serine kinase activity; protein serine/threonine kinase activity; protein kinase activity; protein-containing complex binding
Biological process: protein phosphorylation; flagellated sperm motility; sperm DNA condensation; spermatid development
Cellular component: nucleus; axonemal microtubule doublet inner sheath; sperm flagellum
Genetic constraint (gnomAD): Loss-of-function variants: 9 observed, 6.54 expected, observed/expected ratio (o/e) 1.38, 90% interval 0.8 to 1.91. That is too few expected variants to judge how well the gene tolerates losing a copy. Missense variants: 311 observed, 364.63 expected, observed/expected ratio (o/e) 0.85, 90% interval 0.78 to 0.94. Synonymous variants: 200 observed, 171.69 expected, observed/expected ratio (o/e) 1.16, 90% interval 1.04 to 1.31.
Homologues: Orthologues: chimpanzee TSSK6 (99% identical), macaque TSSK6 (99% identical), pig TSSK6 (99% identical), rabbit TSSK6 (98% identical), dog TSSK6 (98% identical), rat Tssk6 (97% identical), guinea pig TSSK6 (97% identical), mouse Tssk6 (97% identical), zebrafish tssk6 (51% identical), Caenorhabditis elegans C27D6.11 (35% identical), Caenorhabditis elegans Y38H8A.4 (35% identical), Drosophila melanogaster Snrk (35% identical), and 3 more. Paralogues in human: TSSK3 (47% identical), TSSK1B (46% identical), TSSK2 (45% identical), TSSK4 (38% identical), SIK1 (37% identical), NUAK2 (36% identical), HUNK (36% identical), SIK2 (36% identical), SIK3 (36% identical), NUAK1 (34% identical), SNRK (34% identical), PRKAA2 (33% identical), and 5 more.
Diseases named in the same sentence as TSSK6 in open-access papers:
TSSK6 is named in the same sentence as 9 diseases in open-access papers, as found by Europe PMC text mining. Sharing a sentence is not in itself a finding about the gene and the disease. The quoted sentences say what the papers report.
infertile (4 papers, 2016 to 2026). "TSSK6 deletion resulted in an infertile male phenotype caused by certain morphological defects in the sperm." (PMID 33287701, 2020). "Tssk6 KO spermatozoa exhibit severely disturbed morphology and motility, resulting in homozygote infertility and heterozygote subfertility." (PMID 41764189, 2026). "TSSK6 (SSTK)-null mice were found to be infertile due to failure of sperm to relocate Izumo during the acrosome reaction." (PMID 38714941, 2024). "Infertility due to spermatogenic impairment was reported in male TSSK6 knockout mice and in Chinese men exhibiting a triallelic SNP in TSSK6." (PMID 27079378, 2016).
colorectal cancer (2 papers, 2024 to 2025). A primary or metastatic malignant neoplasm that affects the colon or rectum. "Here we find that TSSK6 is frequently anomalously expressed in colorectal cancer and patients with elevated TSSK6 expression have reduced relapse-free survival." (PMID 38762178, 2024). "Our findings establish that TSSK6 exhibits oncogenic activity when abnormally expressed in colorectal cancer cells." (PMID 38762178, 2024). "Depletion of TSSK6 from colorectal cancer cells attenuates anchorage-independent growth, invasion, and growth in vivo." (PMID 38762178, 2024).
asthenozoospermia (1 paper, 2026). "Phenotypic comparisons between Tekt1 and Tssk6 KO mice suggest their involvement in distinct subtypes of asthenozoospermia." (PMID 41764189, 2026).
Azoospermia (1 paper, 2023). Absence of any measurable level of sperm,whereby spermatozoa cannot be observed even after centrifugation of the semen pellet. "Indeed, single-nucleotide mutations of TSSK2, TSSK4, and TSSK6 are reportedly associated with azoospermia and severe oligospermia." (PMID 37149634, 2023).
glioma (1 paper, 2020). A benign or malignant brain and spinal cord tumor that arises from glial cells (astrocytes, oligodendrocytes, ependymal cells). "Using the TCGA data sets, we found that NPR1, DCAF4L2 and TSSK6 were overexpressed in glioma samples compared with adjacent normal tissues in human." (PMID 32452127, 2020). "We found that their homologous genes NPR1, DCAF4L2 and TSSK6 were highly expressed in glioma patients and patients with high NPR1 and TSSK6 predicted a short survival." (PMID 32452127, 2020). "Next, we evaluated the prognostic values of NPR1, DCAF4L2 and TSSK6 in human glioma patients by Kaplan–Meier analysis." (PMID 32452127, 2020). "Taken together, these results demonstrated that NPR1 and TSSK6 may be unfavourable prognostic factors and therapeutic targets for glioma patients." (PMID 32452127, 2020). "Our results suggested NPR1/gcy‐21 and TSSK6/W02B12.12 might be potential targets for glioma therapy via suppressing tumour cell proliferation." (PMID 32452127, 2020). "Notably, NPR1 and TSSK6 were highly correlated with the unfavourable prognosis of glioma patients and could be suitable prognostic indicators in glioma; these need to be confirmed by large clinical samples detection." (PMID 32452127, 2020). "Notably, the expression of homolog gene DCAF4L2/F47D12.9, TSSK6/W02B12.12 and NPR1/gcy‐21 was found to be higher in glioma compared with adjacent normal tissue." (PMID 32452127, 2020).
Insulin resistance (1 paper, 2025). Increased resistance towards insulin, that is, diminished effectiveness of insulin in reducing blood glucose levels. "In summary, we have identified disrupted circadian rhythms in key genes (PER3, ARNTL, TSSK6, HOXB5) in skeletal muscle cells from individuals with T2D, advancing current understanding of how intrinsic timekeeping mechanisms contribute to insulin resistance." (PMID 40495716, 2025).
cancer (6 papers, 2020 to 2025). A tumor composed of atypical neoplastic, often pleomorphic cells that invade other tissues. "TSSK6 (Testis-Specific Serine/Threonine Kinase 6) is primarily expressed in the reproductive system but has been detected in various cancers, including CRC." (PMID 40496862, 2025). "In this context, three separate laboratories have reported TSSK2, TSSK3, and TSSK6 in different cancer types." (PMID 32337545, 2020). "In addition, members of the TSSK family such as TSSK2, TSSK3, and TSSK6 play important roles in survival and proliferation of cancer cells, and TSSK6 is an immunogenic cancer/testis antigen in various cancers." (PMID 37149634, 2023). "Li et al58 discovered TSSK6 expression levels were positively correlated with T‐cell diversity in multiple cancers and TSSK6 could be a putative vaccine target in multiple cancer types." (PMID 32452127, 2020). "Although it is likely that the roles of TSSK6 in cancer and in the testes are not the same, the use of cell culture systems will allow a testable hypothesis to be generated." (PMID 40305308, 2025). "The functional relevance of TSSK6 to cancer, if any, has not previously been investigated." (PMID 38762178, 2024).
tumor (3 papers, 2020 to 2025). "The expression levels of TFRC, LAMC1, PLK1, TYMS, and TSSK6 were significantly higher in tumor tissues while TNFSF14 exhibited higher expression levels in normal tissues." (PMID 40496862, 2025). "Future studies should explore CRISPR-mediated TSSK6 deletion to evaluate its impact on tumor growth and drug resistance." (PMID 40496862, 2025). "Conversely, overexpression of TSSK6 enhances anchorage independence and invasion in vitro as well as in vivo tumor growth." (PMID 38762178, 2024). "Although its role in CRC remains poorly understood, emerging evidence suggests that TSSK6 may contribute to tumor progression through cell cycle regulation and chemoresistance." (PMID 40496862, 2025). "In addition, the mRNA expression of TSSK6 is increased consistently in multiple tumours; however, its protein level in tumour tissues is unknown." (PMID 32452127, 2020). "Specifically, TFRC, PLK1, TYMS, and TSSK6 were remarkably upregulated in tumor tissues compared to normal controls (P < 0.0001)." (PMID 40496862, 2025).
TSSK6 also shares sentences with these, for which no sentence is quoted: colon cancer (1 paper).